FHIP1A (FHF complex subunit HOOK interacting protein 1A)
Description:
Probable component of the FTS/Hook/FHIP complex (FHF complex). FHF complex promotes the distribution of AP-4 complex to the perinuclear area of the cell.
Synonyms: FHIP-L; FAM160A1; FLJ43373
Tractability: PROTAC: ubiquitination databases record sites on it.
Gene: Protein-coding gene on chromosome 4 (151,409,118 to 151,670,503, forward strand). Ensembl gene ENSG00000164142.
Subcellular location (Human Protein Atlas): Cytosol
Gene Ontology:
Molecular function: protein binding
Biological process: protein localization to perinuclear region of cytoplasm; protein transport along microtubule
Cellular component: FHF complex
Genetic constraint (gnomAD): Loss-of-function variants: 53 observed, 75.99 expected, observed/expected ratio (o/e) 0.7, 90% interval 0.56 to 0.88. The upper end of that interval is the gene's LOEUF score, 0.88, which puts it in group 3 of 6, group 1 being the genes least tolerant of losing a copy. Missense variants: 1,087 observed, 1,238 expected, observed/expected ratio (o/e) 0.88, 90% interval 0.83 to 0.92. Synonymous variants: 455 observed, 484.94 expected, observed/expected ratio (o/e) 0.94, 90% interval 0.87 to 1.01.
Homologues: Orthologues: chimpanzee FHIP1A (99% identical), macaque FHIP1A (93% identical), rabbit FHIP1A (88% identical), dog FHIP1A (87% identical), pig FHIP1A (84% identical), mouse Fhip1a (83% identical), rat Fhip1a (83% identical), guinea pig FHIP1A (82% identical), tropical clawed frog fhip1a (60% identical), zebrafish fhip1aa (52% identical), zebrafish fhip1ab (33% identical), Drosophila melanogaster CG3558 (28% identical), and 1 more. Paralogues in human: FHIP1B (36% identical), FHIP2A (15% identical), FHIP2B (15% identical).
Diseases named in the same sentence as FHIP1A in open-access papers:
FHIP1A is named in the same sentence as 1 disease in open-access papers, as found by Europe PMC text mining. Sharing a sentence is not in itself a finding about the gene and the disease.
FHIP1A shares sentences with these, for which no sentence is quoted: tumor (3 papers).